ANLN (anillin, actin binding protein)
Diseases named in the same sentence as ANLN in open-access papers (continued):
Sharing a sentence is not in itself a finding about the gene and the disease.
cancer (continued). "ANLN has been identified as an interactor with KDR that encodes a key receptor mediating the cancer angiogenesis/metastasis switch." (PMID 32560530, 2020). "ANLN is overexpressed in many types of cancers, and there are several studies showing that the upregulation of ANLN is associated with cancer development." (PMID 32560530, 2020). "Although there was a trend showing that ANLN was associated with an aggressive cancer phenotype, an overexpression study is needed to fully demonstrate this point of view because our research was mostly based on the loss-of-function experiments." (PMID 30103211, 2018). "Microarray analysis suggested that ANLN played a major role in cell migration and was closely associated with several cancer-related signaling pathways." (PMID 28600503, 2017). "Furthermore, ANLN has been implicated in various cancer-related activities such as cell growth, infiltration, maintenance of stem cell properties and cytokinesis." (PMID 41513610, 2026). "We therefore probed further into the fourth node in this high-confidence edge network: ANLN/Anillin, a cytoskeletal scaffold protein that links RhoA, actin, and myosin during cytokinesis, with additional emerging nuclear roles in cancer-associated gene transcription." (PMID 36549590, 2023). "Though the underlying mechanism remains unknown, ANLN-regulating cancer stemness could be associated with expressional regulation of a stem cell-specific transcriptional network." (PMID 35340220, 2022). "In addition, ANLN expression was correlated with the number of neoantigens and different phosphorylation pattern in various cancer types, revealing a functional role of genetic mutation accumulation and high phosphorylation in ANLN-mediated oncogenesis." (PMID 35340220, 2022). "Overall, ANLN expression was associated with poor prognosis in most types of cancer." (PMID 35568883, 2022). "To determine risk factors that influence patients’ OS, we then conducted univariate and multivariate regression analyses in seven cancer types, the OS of which was previously demonstrated to be associated with ANLN expression, including ACC, BLCA, BRCA, CESC, LIHC, LUAD, and PAAD." (PMID 36199577, 2022). "Herein, we performed an integrated pan-cancer analysis of ANLN and highlighted its underlying mechanism, which may benefit further exploration of the potential therapeutic options for cancer." (PMID 35340220, 2022). "To date, there is much evidence underpinning the association of ANLN to cancer development." (PMID 32560530, 2020). "However, some studies have shown an association between cancer development and the level of ANLN expression in the nucleus, as well as the role of ANLN outside a cytokinesis event." (PMID 32560530, 2020). "Importantly, we demonstrated that ANLN expression was positively correlated with cancer-associated fibroblasts in BLCA, BRCA-LumA, ESCA, HNSC, human papillomavirus-negative HNSC, KIRC, KIRP, LUAD, MESO, SKCM, metastatic SKCM, THCA, and USC, but negatively correlated with BRCA and TCGT." (PMID 35568883, 2022). "Additionally, we found that high ANLN expression was associated with poor survival in most cancers." (PMID 36199577, 2022). "Recent studies have revealed that ANLN is aberrantly overexpressed in various cancers and promotes malignant progression by regulating oncogenic processes such as proliferation, migration, invasion, and drug resistance." (PMID 41573677, 2025). "As a result, ANLN has the potential to function as a cancer immune biomarker and can be employed in tumor screening, prognosis, tailored therapy planning, and post-treatment monitoring." (PMID 40161493, 2025). "Aberrant expression of ANLN is intricately involved in the molecular pathogenesis of various human cancers and is a potential therapeutic target." (PMID 40723231, 2025).
cancer (continued). "As a key regulatory factor in cytokinesis, ANLN is aberrantly expressed in a wide range of human cancers." (PMID 41573677, 2025). "Studies have demonstrated that up-regulation of ANLN was correlated with several cancers, including those of the liver, pancreas, breast, bladder, esophageal, and lung." (PMID 40405133, 2025). "In conclusion, ANLN is a key regulatory molecule in tumor progression and drug resistance in various cancers." (PMID 41573677, 2025). "In cancer cells, ANLN participates in multiple signaling pathways, including activation of the RhoA/ROCK/myosin II axis, to enhance tumor cell migration." (PMID 41573677, 2025). "This demonstrates that siRNAs are safe and effective in preventing HCC in a large panel of preclinical cancer models, and identifies ANLN as an effective chemoprevention target." (PMID 40704506, 2025). "Research has shown that ANLN promotes the growth of cancer cells by controlling the course of the cell cycle." (PMID 39968094, 2025). "Moreover, ANLN’s role in LUAD may also be associated with preventing pyroptosis in cancer cells." (PMID 40486872, 2025). "Recent studies show that aberrant expression of ANLN is observed in multiple types of cancer, and that overexpression of ANLN is a useful biomarker predicting cancer cell metastasis and patient prognosis." (PMID 40723231, 2025). "We performed a head-to-head comparison of N-acetylgalactosamine (GalNAc)-conjugated small interfering RNA (siRNA)-mediated inhibition of five genes (CDK1, PD-L1, CTNNB1, SMYD3, ANLN) to prevent cancer in four distinct autochthonous HCC mouse models." (PMID 40704506, 2025). "Recent research has identified ANLN’s function in the initiation and advancement of different cancers." (PMID 38398143, 2024). "Recent studies have revealed the involvement of ANLN in the initiation and progression of various cancer types." (PMID 38398143, 2024). "Further analysis of the model genes within MOCM across pan‐cancer settings revealed that ANLN, CCNB1, CDKN3, EXO1, GJB3 and RAD51AP1 were predominantly overexpressed in tumour tissues, while GGT6 and CYP4B1 were highly expressed in normal tissues." (PMID 38958523, 2024). "Our siRNA-mediated knockdown assays demonstrated that the downregulation of ANLN significantly inhibited cancer cell proliferation, invasion, and migration abilities, and is strongly suggested as a cancer-promoting gene in BC cells." (PMID 39728605, 2024). "ANLN expression and localization have been shown to be dynamic 27 and ANLN is primarily nuclear in cancer cells, with only a weak cytoplasmic staining observed, as reported by most of the published clinical investigations." (PMID 36923927, 2023). "Earlier research has revealed that ANLN exhibits an important part in a variety of cancer related mechanisms, which includes cancer initiation, growth, angiogenesis, and metastasis." (PMID 36923927, 2023). "ANLN upregulation is associated with higher TMB, MSI, and immune cell infiltration in multiple types of tumors, shedding new light for cancer treatment." (PMID 36030492, 2023). "Subsequently, patients were divided into an ANLN high expression group and an ANLN low expression group to explore the mechanism by which ANLN promotes cancer." (PMID 37741887, 2023). "Our study is the first to comprehensively analyze the expression pattern of ANLN and its correlation with patients' prognosis and immune features in 31 different types of cancers." (PMID 36030492, 2023). "In HCC it was reported that ANLN promotes hepatic carcinogenesis as well as cancer cell proliferation 20, 22-24." (PMID 36923927, 2023). "Cox regression and Kaplan–Meier analysis were utilized to assess the prognostic value of ANLN in pan‐cancer." (PMID 36030492, 2023). "Based on the evidence supporting the correlation of ANLN with acknowledged features of cancer, ANLN should be considered as a novel target for cancer therapy." (PMID 37007961, 2023).
cancer (continued). "While the activities of nuclear ANLN in tumorigenesis have been unexpectedly overlooked, the nuclear localization of ANLN in many cancer cells has been thoroughly described." (PMID 36923927, 2023). "Our study firstly analyzed the expression pattern of ANLN in tumor and normal samples from the TCGA pan‐cancer dataset." (PMID 36030492, 2023). "While in almost all cancer types, ANLN expression was less expressed in the C3 (inflammatory) immune subtype, a subtype featured with the best patient’ survival outcomes, as previous work has demonstrated." (PMID 36199577, 2022). "KEGG analysis and the STRING tool were used to elucidate the potential mechanism of ANLN in cancer development." (PMID 35340220, 2022). "We used the MethSurv to investigate DNA methylation of ANLN in terms of the prognostic value of each CpG site in cancer." (PMID 35991576, 2022). "In conclusion, the present study demonstrated that ANLN expression is closely related to poor prognosis in various cancers." (PMID 35340220, 2022). "The infiltration levels of MDSC (myeloid-derived suppressor cells) and nature kill T cells (T cell NK) positively and negatively correlated with ANLN expression in most cancer types, respectively." (PMID 36199577, 2022). "To analyze the molecular mechanism of the ANLN in the tumor progression, we further explored the function of ANLN in cancers by analyzing the enrichment of ANLN-relevant genes and proteins." (PMID 35340220, 2022). "Subsequently, we systematically explored the relationships of ANLN expression with patient prognosis, genetic alterations, phosphorylation, the immune microenvironment, and gene function in order to uncover the molecular mechanisms of ANLN in cancer." (PMID 35568883, 2022). "By TISIDB, we explored the differential ANLN expression in different immune and molecular subtypes in pan-cancer." (PMID 36199577, 2022). "To explore the potential pathways of ANLN participating in pan-cancer, we then conducted a GSEA analysis based on the Reactome pathway database." (PMID 36199577, 2022). "Meanwhile, ANLN was upregulated in the early stages in 17 types of cancer and exhibited good predictive accuracy in many cancer types." (PMID 36199577, 2022). "The current research first explored ANLN expression in pan-cancer and identified that both mRNA and protein levels of ANLN expression were upregulated in most tumor tissues compared to normal tissues." (PMID 36199577, 2022). "To conclude, this pan-cancer analysis shed light on the pivotal carcinogenic roles of ANLN and paved the way for future ANLN research in solid tumors." (PMID 36199577, 2022). "Although the biological functions of ANLN have been extensively studied, few comprehensive analyses have examined the specific roles of ANLN in various cancers." (PMID 35568883, 2022). "We further assessed the correlation between the expression levels of ANLN and TME in various cancers and found that it was negatively associated with the ImmuneScore in STAD but positively associated with the ImmuneScore in THCA and KIRC." (PMID 35340220, 2022). "The results from TCGA database displayed the discrepancy of ANLN expression levels in tumor and adjacent normal tissues in individual cancer samples, thereby revealing ANLN expression specificity." (PMID 35340220, 2022). "Secondly, the detailed carcinogenesis mechanisms of ANLN in pan-cancer need to be fully addressed further by experiments conducted in vitro and in vivo." (PMID 36199577, 2022). "However, the pathogenic role of ANLN in various cancers remains unclear." (PMID 35991576, 2022). "Overall, ANLN had moderate to strong power to predict tumor tissues and normal tissues except for a small number of cancer types like GBM, KICH, LGG, and PRAD." (PMID 36199577, 2022). "The results also indicated that ANLN expression was mainly related to poor prognosis in most cancer types, except THYM." (PMID 35340220, 2022).
cancer (continued). "As a result, when compared to normal tissues, ANLN expression is elevated in most cancers, and its expression also differs in different immune subtypes and molecular subtypes in diverse cancers." (PMID 36199577, 2022). "Based on our findings regarding the expression of ANLN in different cancer types, patients were segmented into high and low expression groups to investigate the correlation of ANLN expression with prognosis." (PMID 35568883, 2022). "A total of 7 cancer types whose prognoses were inversely correlated with ANLN expression were incorporated in our analysis, including ACC, BLCA, BRCA, CESC, LIHC, LUAD, and PAAD." (PMID 36199577, 2022). "Due to the insufficient sample size of normal tissues in TCGA, we combined the data of normal and tumor tissues of GTEx and TCGA databases to evaluate the differential expression of ANLN in 27 cancer types." (PMID 35340220, 2022). "Due to its crucial roles in cell growth, migration, and cytoplasmic division, researchers have studied the role of ANLN in malignant tumors." (PMID 36199577, 2022). "Our GO and KEGG enrichment analysis using the ANLN co-expressed genes in pan-cancer revealed that ANLN participated in key biological processes involved in the cell cycle like organelle fission, nuclear division, and chromosome segregation." (PMID 36199577, 2022). "We subsequently evaluated ANLN expression levels in 21 different human cancer cell lines from the CCLE database." (PMID 35340220, 2022). "In the final, we observed that the expression of immunoinhibitors was closely related to ANLN in pan-cancer." (PMID 36199577, 2022). "Accordingly, in this study, we evaluated the carcinogenic roles of ANLN in various cancer types using online databases." (PMID 35568883, 2022). "This indicated that in some cancers, ANLN expression had an important role in tumor immunity by regulating the expression pattern of immune checkpoints." (PMID 35340220, 2022). "We analyzed ANLN expression in 33 different cancers using public databases including TCGA, CPTAC, and GEO." (PMID 35340220, 2022). "Accordingly, in this study, we conducted a pan-cancer analysis of ANLN using TCGA and GEO databases." (PMID 35568883, 2022). "In general, our study contributes to uncovering the tumor-promoting effect of ANLN in diverse cancers, and we comprehensively describe the value of ANLN in the tumor microenvironment, patient prognosis and diagnosis." (PMID 36199577, 2022). "Anillin (ANLN), as an oncogene in several types of human cancers, has a positive effect on tumorigenesis." (PMID 36482354, 2022). "We analyzed the first 100 genes that correlated with ANLN expression in cancer expression datasets of TCGA by using the GEPIA2 tool." (PMID 35340220, 2022). "The current work started with a pan-cancer expression and survival investigation of ANLN, and the findings revealed that ANLN was upregulated in the majority of cancers." (PMID 36199577, 2022). "Based on public data, ANLN can promote cell proliferation and growth in cancer and increase cell migration and invasion." (PMID 34082790, 2021). "AIM1L serves as an independent prognosis predictor for OS in HCC patients after adjusting TTK, ANLN and person neoplasm cancer status (HR = 1.5, 95%CI = 1.02–2.1, P = 0.037)." (PMID 34130591, 2021). "For example, the upregulation of ANLN is observed in various cancers including ovarian, lung, hepatic, pancreatic, colorectal, and breast cancer." (PMID 33854062, 2021). "After the 5-fold cross validation, parameters including TTK, ANLN, AIM1L and person neoplasm cancer status were recruited to be underlying candidates of OS in HCC patients when λ took the minimum value." (PMID 34130591, 2021). "The LASSO model showed that TTK, ANLN, AIM1L and person neoplasm cancer status should be underlying candidates of OS in HCC." (PMID 34130591, 2021).
cancer (continued). "Here, we gather evidence to determine the applicability of ANLN as a prognostic tool for some types of cancer, and the impact that ANLN has on the hallmarks of cancer." (PMID 32560530, 2020). "In the case of normal cells, the number of times proliferation occurs is more limited than that of cancer cells, so the toxic effect of suppressing ANLN is thought to be limited." (PMID 32560530, 2020). "The regulation of actin-binding protein ANLN through anti-tumour miR-217 suppressed cancer cell aggressiveness in pancreatic ductal adenocarcinoma." (PMID 32560530, 2020). "ANLN expression was documented to be upregulated from ~2- to 6-fold in cancer tumours compared to normal ones, except brain tumours." (PMID 32560530, 2020). "In fact, in some cancers, ANLN is also found in the cytoplasm, suggesting the existence of nonproliferation-associated activities of ANLN." (PMID 32560530, 2020). "Although its function was unclear, nucleus ANLN was supposed to play a role in a poor cancer prognosis." (PMID 32560530, 2020). "The value of ANLN as a biomarker in cancer seems to be high, and the development of ANLN inhibitors by considering ANLN as a therapeutic option in cancer seems to be worth further consideration." (PMID 32560530, 2020). "We have introduced a concise summary of ANLN as a biomarker and as a novel target of cancer development." (PMID 32560530, 2020). "While the tumour microenvironment is considered to be a key contributor to the development of cancer, there is scant research as to the impact of ANLN on the characteristics of the microenvironment, particularly on inflammation and immunity." (PMID 32560530, 2020). "Upregulation of ANLN expression is frequently observed during cancer development, growth, and progression." (PMID 32536039, 2020). "A high upregulation of ANLN was found in several cancers, and this protein plays an important role in cytokinesis and is a scaffold to a variety of proteins." (PMID 32560530, 2020). "Anilin actin binding protein (ANLN) and transducing-like enhancer protein 2 (TLE2) are associated with cancer patient survival and progression." (PMID 31766561, 2019). "Functionally, increasing evidence has indicated that ANLN is critical for growth and metastasis of cancer cells." (PMID 31395079, 2019). "In silico RNA-seq data from the Cancer Cell Line Encyclopedia showed ANLN and TLE2 expression levels in TPM (transcripts per million) for 25 BLCA cell lines, with different molecular subtypes of each (basal, luminal, and mixed)." (PMID 31766561, 2019). "In order to get a whole image of ANLN expression profile in human cancer, we searched the TCGA database and found that transcription level of ANLN was upregulated in nearly all types of the listed human cancer." (PMID 30103211, 2018). "Consistent with its prominent role in cytokinesis, dysregulated ANLN expression has long been observed in the development and progression of various human cancers." (PMID 30103211, 2018). "In contrast to the large number of articles describing ANLN’s downstream effects, limited research has been designed to investigate the mechanism leading to the dysregulation of ANLN in cancer development." (PMID 30103211, 2018). "Expression of ANLN enhanced cancer cell aggressiveness and its high expression predicts poorer survival of PDAC patients." (PMID 28881803, 2017). "As indicated in the GSE31684 dataset, published by Memorial Sloan-Kettering Cancer Center with 93 patients with high-risk BLCA, the ANLN expression level, on average, significantly increased as tumor stage progress (ANOVA test, P = 0.006)." (PMID 28600503, 2017). "Dysregulated ANLN expression has been found in a wide variety of human cancers, i.e. breast, colorectal, endometrial, liver, lung, renal, kidney, ovarian, and pancreatic cancer." (PMID 28600503, 2017). "Compared with control cells, multinucleated cancer cells were observed at higher frequency after ANLN knockdown." (PMID 28600503, 2017).